PPARA (peroxisome proliferator activated receptor alpha)
Diseases named in the same sentence as PPARA in open-access papers (continued):
Sharing a sentence is not in itself a finding about the gene and the disease.
Hepatic steatosis (continued). "Statins may reduce hepatic steatosis by activating sterol regulatory element-binding proteins (SREBPs), peroxisome proliferator-activated receptor alpha (PPARα), and β-oxidation, even if their beneficial effects in experimental steatosis remain controversial." (PMID 36769582, 2023). "MiR-155 directly decreases PPARα in hepatocytes, thus promoting hepatic steatosis." (PMID 38067261, 2023). "The SREBP-1c/PPARα ratio has been reported as a good marker for hepatic steatosis." (PMID 36937300, 2023). "However, previous studies have found that saikosaponin alleviates hepatic steatosis in hybrid grouper by activating the AMPK/PPARα signaling pathway after the fish consume a high-lipid diet (15% crude fat)." (PMID 37760294, 2023). "Additionally, mice receiving 12 weeks of Lieber-DeCarli liquid diet showed decreased PPARα expression, with hepatic steatosis, necrosis, and inflammatory infiltration indicating a key role of PPARα in alcohol-mediated steatosis and liver injury." (PMID 37239997, 2023). "A hepatocyte-specific PPARα gene knockout mouse model also shows hepatic steatosis during fasting." (PMID 38089874, 2023). "It has been shown that a partial activator of PPARγ, telmisaten, in combination with activating PPARα in the liver, could alleviate hepatic steatosis in mice that were fed a high-fat diet." (PMID 37096195, 2023). "Through this interaction, CtBP2 represses PPARα, which may contribute to hepatic steatosis and other metabolic inflexibilities in obese liver." (PMID 37286039, 2023). "Finally, HFD-fed genetically engineered mouse model demonstrated that liraglutide ameliorated lipid-induced hepatic steatosis though the HIF-2α/PPARα pathway." (PMID 37079136, 2023). "Given the improvement in hepatic steatosis after PPARα activation, we hypothesized the B2D+ fenofibrate treatment caused inversion of the alignments between B2D and NAFLD transcription networks." (PMID 37417957, 2023). "In rodents, PFAAs-induced liver steatosis and toxicity have been mainly attributed to PPARα, which activation leads to increased expression of genes involved in FAO, lipogenesis (Srebf1, sterol regulatory element-binding transcription factor 1; Fasn, fatty acid synthase), and lipid uptake (Cd36)." (PMID 37242221, 2023). "Moreover, WBJ and BGE enhanced the activation of AMPK to reduce SREBPs, fatty acid synthase, and HMG-CoA reductase but increased the expression of CPT-I and PPARα to improve hepatic steatosis." (PMID 37630688, 2023). "The study revealed that an adequate VD level may act as a protective factor in NAFLD and that VD may alleviate hepatic steatosis via the PPARα signaling pathway." (PMID 37033263, 2023). "Concurrent activation of LXR and PPARα exacerbates hepatic steatosis in HFD-induced obese mice." (PMID 35614477, 2022). "Our study found that SX reduced hepatic steatosis, the levels of alanine aminotransferase, aspartate aminotransferase, total cholesterol, and triglyceride and apoB48 expression but increased peroxisome proliferator activated receptor α (PPARα) level." (PMID 35837380, 2022). "Reduced p-CREB expression exacerbates HFD-induced hepatic steatosis by downregulating PPARα, whereas activated p-CREB reduces PPAR-γ expression to regulate the hepatic DNL, which was confirmed by the downregulation of DNL-related ACC1 and FAS in GAS5 knockdown cells." (PMID 35957809, 2022). "Taken together, our findings demonstrated that SSC could be a dual activator of AMPK/PPARα, thereby ameliorating hepatic steatosis in HepG2 cells." (PMID 35628280, 2022). "Hence, PPARA activation performs an important role in the alteration of hepatic steatosis and steatohepatitis because of its effects on the facilitation of the fatty acid oxidation system and downregulation of inflammatory response." (PMID 36432581, 2022). "Similar to our findings, drinking a taurine solution could upregulate PPARα and shows preventive effects on the development of hepatic steatosis in high-fat/CHOL -fed hamsters." (PMID 35883883, 2022).
Hepatic steatosis (continued). "Gilbert’s syndrome, a mouse model that shows the protective effect against hepatic steatosis, might be mediated by increased PPARα protein levels due to the reduction of S73 phosphorylation." (PMID 36589809, 2022). "Moreover, TET1 knockout mice resulted in a higher degree of liver steatosis and lower levels of PPARα and its target genes." (PMID 36551797, 2022). "Since the inhibition of miR-34a in a mice model improved hepatic steatosis by increasing PPARα levels promoting lipid oxidation, targeting miR-34a/PPARα signaling holds promise as an interesting future strategy for clinical miRNA therapeutic applications against NAFLD." (PMID 36551797, 2022). "In conclusion, this study demonstrates that LNT may ameliorate hepatic steatosis and decrease oxidative stress and apoptosis by activating the PPARα pathway and is a potential drug target for NAFLD." (PMID 35050176, 2022). "Therefore, PPARα agonists and their modulators are used as a strategy for the management and treatment of fatty liver." (PMID 36164476, 2022). "Abnormal circRNA_0046366, circRNA_0046367/miR-34a/PPARα signal transduction may be a new potential target to treat hepatic steatosis." (PMID 35595755, 2022). "A diet that activates PPARα may be effective for preventing the development of fatty liver due to excessive sugar intake." (PMID 36140300, 2022). "However, some studies suggest that long-term activation of PPARα induced hepatocellular carcinoma in mice and was essential for the development of hepatic steatosis." (PMID 36589809, 2022). "Furthermore, we evaluated SSC as a novel AMPK/PPARα dual activator and its ability to counteract hepatic steatosis in HepG2 cells." (PMID 35628280, 2022). "In addition, hepatocyte-specific PPARα deletion in mice showed a marked increase in hepatic steatosis, increased plasma FFA, and impaired ketone bodies in response to two weeks of HFD feeding." (PMID 35050176, 2022). "This suggests that LZG could alleviate hepatic steatosis by regulating PPARα signaling to promote β-oxidation of fatty acid." (PMID 35035496, 2022). "Studies have shown that PPARα regulates lipid metabolism in the liver, and abnormalities may lead to hepatic steatosis and hepatocellular carcinoma." (PMID 35743814, 2022). "Moreover, Tff3 was shown to directly bind to the promoter region of peroxisome proliferator-activated receptor alpha (Pparα) and upregulate its expression, which subsequently reduced hepatic steatosis by increasing the fatty oxidation process in the liver." (PMID 36013467, 2022). "A diet that activates PPARα may be effective for preventing the development of fatty liver due to excessive sucrose intake." (PMID 36140300, 2022). "Moreover, overexpression of hepatic HSL and ATGL activates PPARα-targeted fatty acid oxidation gene expression and improves hepatic steatosis." (PMID 35883883, 2022). "In addition, the natural compound magnolol counteracts hepatic steatosis via AMPK-dependent PPARα activation." (PMID 35628280, 2022). "The decrease in hepatic steatosis was accompanied by decreased expression of lipogenic genes, including Srebp1c and stearoyl-CoA desaturase 1 (Scd1), and increased expression of β-oxidation-related genes, such as Pparα and Cpt-1α." (PMID 33794740, 2021). "Hepatocyte PPARα-specific knockout mice exhibited severe HFD-induced hepatic steatosis 60,61." (PMID 33500723, 2021). "PPARα is a transcription factor involved in the process of lipid oxidation and consequent metabolism of carbohydrates and lipids, noting that its activation is related to an increase in hepatic steatosis and inflammation." (PMID 33693024, 2021). "Interestingly, it was also reported that using combined supplementations such as DHA and HT is warranted to prevent liver steatosis through regulating PPARα and Nrf2 signals." (PMID 33603948, 2021).
Hepatic steatosis (continued). "On the contrary, alcohol can reduce the activity of the PPARα signaling pathway, which decreases the fatty acids (FAs) ß-oxidation, thereby further promoting lipid accumulation in hepatocytes and ultimately leading to hepatic steatosis." (PMID 35003311, 2021). "It was found that when liver PPARα was specifically knocked out, liver steatosis would increase." (PMID 34262459, 2021). "In addition, activated AMPKα can repress fat accumulation and hepatic steatosis by regulating downstream gene PPARα and SREBP-1, known as two important transcription factors in lipid metabolism." (PMID 34621322, 2021). "Previous studies have suggested that the activation of PPARα could improve hepatic steatosis, inflammation, and fibrosis by enhancing fatty acid oxidation." (PMID 34285335, 2021). "Typically, fatty liver can be ameliorated by reducing lipid uptake and the suppression of de novo lipid synthesis as well as increased lipid oxidation and enhanced lipid excretion, actions orchestrated by Srebp1c and PPARα." (PMID 34768897, 2021). "The role of PPARα in fatty liver disease has been investigated in the past decade." (PMID 34603062, 2021). "We speculate that old mice with a large number of senescent liver cells might secrete HMGB1 which activates the RAGE/PPARα axis to promote hepatic steatosis." (PMID 32936538, 2020). "PPARα regulates lipid metabolism in the liver, the organ that largely controls whole-body nutrient/energy homeostasis, and its abnormalities may lead to hepatic steatosis, steatohepatitis, steatofibrosis, and liver cancer." (PMID 32192216, 2020). "Finally, we explored the clinical relevance of the RAGE/PPARα axis to hepatic steatosis in aging individuals." (PMID 32936538, 2020). "Fenofibrate treatment, a peroxisome proliferator-activated receptor α (PPARα) stimulant, not only restored peroxisome deficits and improved mitochondrial function but also reduced hepatic steatosis, demonstrating a critical peroxisome-mitochondrion role in undernutrition-induced fatty liver." (PMID 32900869, 2020). "Recent studies have shown that Periostin could promote liver steatosis and through suppression of PPARα and fatty acid β-oxidation." (PMID 31918919, 2020). "However, the better efficacy in improving hepatic steatosis by exercise in the GCN2-deficient mice enhanced liver lipid metabolism, at least partially, via the AMPK/SIRT1/PPARα pathway." (PMID 33299856, 2020). "In addition, Pparα has been reported to attenuate liver steatosis and inflammation in NASH, and agonists for Pparα have been shown to have therapeutic potential for NASH." (PMID 31086120, 2019). "Additionally, they aimed to predict the impact of activating PPARα by lipids and showed that PPARα activation appears to have a significant role in hepatic steatosis progression, suggesting issues with PPARα agonists as treatment options." (PMID 31771247, 2019). "MD001 alleviated fatty liver by reducing TG and FFA levels in db/db mice, which was associated with increased expression levels of ACOX, CPT, and MLYCD and decreased expression levels of ADD1, ACC, and FAS by PPARα activation." (PMID 30733541, 2019). "In our current study, overexpression of miR-30c significantly reduced PPARα activity in heart of db/db mice, which might contribute to the remission of concurrent hyperlipidemia and hepatic steatosis." (PMID 30635067, 2019). "Dysregulation of PPARα dependent fatty acid oxidation promotes hepatic steatosis." (PMID 30975991, 2019). "As these data collectively suggest that GPS2 promotes the progression of fatty liver disease via antagonizing PPARα, the selective therapeutic modulation of GPS2–PPARα interactions could be of interest for future disease interventions." (PMID 30975991, 2019). "Our result also give a comprehensive profile of hepatic lipid metabolism and suggested that PPARα may be the key regulator in the gut microbiota induced hepatic steatosis." (PMID 30079055, 2018).
Hepatic steatosis (continued). "Paradoxically, liver-specific FASN knockout promoted hepatic steatosis in mice on a zero-fat diet, in which steatosis developed alongside defective PPARα signaling and with a phenotype that could be corrected by dietary fat or a PPARα agonist." (PMID 29936596, 2018). "Using chronic treatment with insulin and/or human chorionic gonadotropin (hCG), we showed that all female rats with different treatments induced imbalance between de novo lipogenesis and mitochondrial β-oxidation via the Pparα/β–Srebp1/2–Acc1 axis, resulting in varying degrees of hepatic steatosis." (PMID 29719598, 2018). "We observed increases in both Ppara and Pparg mRNA expression in rats regardless of treatment with insulin and/or hCG, and this suggests that the induction of varying degrees of hepatic steatosis by the different treatments depends on the balance between PPARα and PPARβ activity." (PMID 29719598, 2018). "In the present study, males had a reduction in both Sirt1 and PPARα, which is indicative of the mechanism through which lipid accumulation occurs in the liver, and that may contribute to the genesis of hepatic steatosis." (PMID 30304827, 2018). "PPARα downregulation decreased PPARα-mediated lipid metabolism and led to hepatocellular steatosis, which indicated that circRNA_0046367/miR-34a/PPARα axis might be involved in lipoxidative and reduce hepatic steatosis-inducing HCC." (PMID 30191143, 2018). "In this line of evidence, hepatic lipid accumulation leads to the aberrant histone H3K4 and H3K9 methylation in PPARα and lipid catabolism related genes, suggesting that histone methylation may contribute to hepatic steatosis and disease progression." (PMID 29844386, 2018). "Additionally, the critical role of PPARα in preventing fat-induced nonalcoholic steatohepatitis by alleviating liver steatosis, oxidative stress, and inflammation has been proven." (PMID 30538803, 2018). "Moreover, animal studies along with histological findings also demonstrated the beneficial role of HIET in reducing body weight gain, plasma lipid levels, and regulating the AMPK/SREBP/PPARα signaling cascade to reduce hepatic steatosis." (PMID 29968750, 2018). "Because of the opposite actions of PPARα and PPARγ on hepatic steatosis, the “spillover” effects of these PPAR agonists might prevent a net gain in their ability to reduce TG accumulation in the liver." (PMID 30566427, 2018). "A chronic high-fat diet led to severe hepatic steatosis in Pparα-null mice." (PMID 28855656, 2017). "Because fatty liver may be accompanied by hepatic inflammation and PPARα regulates inflammation, the effects of MHY553 on inflammation were investigated." (PMID 28545035, 2017). "Altogether, these results suggest that miR-21 may contribute to NASH development not only through PPARα inhibition, ultimately inducing cell inflammation and fibrosis, but also by promoting liver steatosis and lipoapoptosis." (PMID 28406477, 2017). "We hypothesized that hepatic steatosis might be prevented by stimulating hepatic fatty acid oxidation through PPARα activation." (PMID 28159867, 2017). "Our results demonstrated that pioglitazone attenuating the hepatic steatosis may be mediated by enhancing cytosolic lipolysis, β-oxidation and autophagy in a PPARα and PPARγ dependent manner." (PMID 28831172, 2017). "The results of this study indicate that CnP inhibits steatohepatitis, possibly through the inhibition of hepatic TGF-β mRNA levels, and induces an increase in PPARα mRNA levels, resulting in the attenuation of hepatic steatosis, inflammation, and fibrosis in mice." (PMID 28594915, 2017). "Theoretically, activation of the PPARα, such as fenofibrate, could be a promising strategy to treat hepatic steatosis." (PMID 28831172, 2017). "Because several canonical PPARα targets promote increased fatty acid oxidation, it was speculated that patients with a fatty liver would benefit from a treatment with fibrates." (PMID 28874443, 2017).
Hepatic steatosis (continued). "Earlier evidence indicated that PPARα−/− mice had severe hepatic steatosis." (PMID 29056891, 2017). "In these subjects, fenofibrate or other, more potent PPARα activators or modulators could be an effective therapeutic for reducing fatty liver disease." (PMID 28159867, 2017). "In hepatic steatosis, expression of several genes is dysregulated, including PPARγ and PPARα." (PMID 27611931, 2016). "Therefore, dietary alternation dynamically activates PPARα-dependent signaling and promotes the utilization of hepatic lipids, protecting the mice from developing fatty liver." (PMID 27189661, 2016). "PPARα increases hepatic fatty acid oxidation and prevents hepatic steatosis." (PMID 27611931, 2016). "PPARα-KO mice are known to be susceptible to fasting induced hepatic steatosis; therefore before the sacrifice, mice were not fasted." (PMID 26604919, 2015). "Hence, several PPARα agonists increase hepatic steatosis, which results in the development of this side effect." (PMID 26168156, 2015). "In addition, the expression of PPARα was increased in HFD-induced hepatic steatosis mice treated with the miR-34a inhibitor compared to the HFD-induced hepatic steatosis mice treated with the NC duplex." (PMID 26330104, 2015). "Importantly, it is possible that the deterioration of hepatic steatosis with pioglitazone treatment in obese DIO mice was a species-specific manifestation, similar to the hepatomegaly caused by PPARα agonists in rodents." (PMID 26035752, 2015). "However, in lean mice Cidec is regulated by Pparα, and recent research showed that simultaneous activation of Pparα and silencing of Cidec protected diet-induced obese mice from hepatic steatosis." (PMID 26193881, 2015). "Taken together, these results suggested that the HFO diet did not elicit hepatic insulin resistance but that it induced a lower degree of hepatic steatosis compared to the HL diet, possibly through an ameliorated utilisation of lipid substrates mediated by PPARα." (PMID 24663492, 2014). "We observed a significant increase of HSP72, PPARα and Sirt1 with amelioration of hepatic steatosis, particularly in the combined treatment group, suggesting that not only vildagliptin, but also valsartan may participate in activating this pathway." (PMID 24188631, 2013). "In this study, we addressed the hypothesis that excess fat plays a central role in the pathogenesis of hepatic steatosis resulting from the overexpression of PPARα, PPARγ, and UCP2." (PMID 24086674, 2013). "The role of PPARα in the pathogenesis of fatty liver became evident in PPARα KO mice." (PMID 23431284, 2013). "Thus, PPARα activation by n-3 PUFA supplementation ameliorated hepatic steatosis in obese NAFLD patients." (PMID 22675337, 2012). "Synthetic agonists for PPARα stimulate the expression of genes involved in peroxisomal and mitochondrial fat oxidation, whereas deficiency of PPARα signaling impairs the induction of FAO genes and results in hepatic steatosis following starvation." (PMID 23133608, 2012). "Given the antiobesity and anti-inflammatory properties of PPARα and PPARγ, pharmacological interventions targeting these transcription factors could be a promising strategy to treat hepatic steatosis in patients undergoing I/R." (PMID 22675337, 2012). "In this study, we explored whether 13-oxo-ODA acts as a PPARα agonist in vitro and ameliorates dyslipidemia and hepatic steatosis in vivo." (PMID 22347463, 2012). "In this study, we explored the possibility that 13-oxo-ODA acts as a PPARα agonist in vitro and whether its effect ameliorates dyslipidemia and hepatic steatosis in vivo." (PMID 22347463, 2012). "We examined the role of mouse and human PPARα in TRI-induced hepatic steatosis and toxicity." (PMID 20709644, 2010). "Our findings demonstrated that improvement of fatty liver by SSC may be through the enhancement of PPARα-mediated β-oxidation." (PMID 20211032, 2010).